LRIG3 (leucine rich repeats and immunoglobulin like domains 3)
Diseases named in the same sentence as LRIG3 in open-access papers (continued):
Sharing a sentence is not in itself a finding about the gene and the disease.
cardiac hypertrophy (1 paper, 2022). "In Lrig3−/− mice, investigators showed that aging mice demonstrated cardiac hypertrophy and low plasma HDL-C levels." (PMID 35501457, 2022).
cervical cancer (1 paper, 2017). A primary or metastatic malignant neoplasm involving the cervix. "The expression of the human leucine-rich repeats and immunoglobulin-like domains (LRIG) proteins LRIG1, LRIG2, and LRIG3 has emerged as a new potential prognostic biomarker in different types of human cancer, including cervical cancer." (PMID 28841699, 2017). "In general, high expression of LRIG1 and LRIG3 in tumours is associated with improved survival in cancer patients, whereas high expression of LRIG2 is associated with poor survival even in early-stage cervical cancer patients." (PMID 28841699, 2017).
cognitive decline (1 paper, 2021). "Its upregulation ameliorated cognitive decline, inhibited apoptosis, and increased survival of neurons by targeting LRIG3." (PMID 33790780, 2021).
endometrial cancer (1 paper, 2021). Primary or metastatic malignant neoplasm involving the endometrium (mucous membrane that lines the endometrial cavity). "As a result, we found that one of the LRIG proteins—LRIG3—might influence endometrial cancer survival rates." (PMID 33802837, 2021).
lung carcinoma (1 paper, 2010). "We observed decreased levels of proteins in the serum of lung cancer patients compared to controls, including cadherin-1, LRIG3, sL-selectin, SCRsR, ERBB1 and RGM-C." (PMID 21170350, 2010).
ovarian carcinoma (1 paper, 2013). A malignant neoplasm originating from the surface ovarian epithelium. "Although each alteration is infrequent, ROS1 fusions with many kinds of 5′ partner genes (CCDC6, CD74, EZR, KDELR2, LRIG3, SDC4, SLC34A2 and TPM3) have been reported in lung, brain, biliary tract, and ovarian cancers." (PMID 23418494, 2013).
periodontitis (1 paper, 2022). An acute or chronic inflammatory process that affects the tissues that surround and support the teeth. "Consequently, hsa-miR-203/IL6 and hsa-miR-671-5p/LRIG3 were identified as potential regulatory pathways in periodontitis." (PMID 35397550, 2022).
type 2 diabetes (1 paper, 2021). "Nevertheless, LRIG1, LRIG3, or other functionally associated proteins may provide novel targets for the prevention or treatment of type 2 diabetes or other metabolic diseases." (PMID 33469151, 2021).
tumor (16 papers, 2015 to 2026). "More specifically, circ-LRIG3 expression is linked with aggressive tumor features, including increased tumor size, advanced TNM stage, and vascular invasion." (PMID 34205978, 2021). "Importantly, when nude mice were treated with C188–9, the increased tumor size and lung metastasis nodules caused by circ-LRIG3 overexpression were restored to control levels." (PMID 33222697, 2020). "While LRIG2 has been described as a tumor promoter, LRIG1 and LRIG3 have been identified as tumor suppressors in previous literature." (PMID 41201961, 2025). "The less studied LRIG3, which is said to have similar functions to LRIG1, has also been described as a tumor suppressor and is linked to lower tumor grades and a better patient survival." (PMID 41201961, 2025). "On the other hand, several oncogenic circRNAs (circRHOT1, circMAT2B, circASAP1, circMET, circ-LRIG3, and circRNA_104348) have been recognized to promote tumor growth and metastasis in HCC19–25." (PMID 38589413, 2024). "Bioinformatics analysis based onalgorithm Gene set enrichment analysis showed that in LRIG3-high group of TCGA GBM cohort, M1/ M2-like tumor-associated macrophages were significantly decreased, while CD8+ T cells were increased." (PMID 36639372, 2023). "The results of western bloting showed that LRIG3 was preferentially expressed by tumor cell line rather then TAMs in huamn/mouse cell lines." (PMID 36639372, 2023). "Soluble LRIG3 can suppress the M2-like polarity transformation of TAMs and inhibit the growth of tumor." (PMID 36639372, 2023). "Herein, we find that LRIG3 is preferentially expressed by GBM tumor cells compared with TAMs in TME." (PMID 36639372, 2023). "While LRIG1 and LRIG3 are thought to be tumor suppressors, LRIG2 expression is mostly related to poor prognosis." (PMID 33786987, 2021). "Analyses of LRIG3 in glioblastoma cells showed that the gene is a potent tumor suppressor, which plays a role in invasion, proliferation, and apoptosis." (PMID 33802837, 2021). "At the molecular level, the encoded transmembrane protein LRIG1 acts as a negative regulator of growth factor signaling; the LRIG2 protein works as a tumor promotor; and the LRIG3 protein functions as a tumor suppressor." (PMID 33802837, 2021). "Our previous study has shown that LRIG3 functions as a tumor suppressor by attenuating phosphorylation of the ERK and AKT signaling pathways." (PMID 33718179, 2021). "Previously, we demonstrated that LRIG3 functions as a tumor suppressor by inactivating the ERK and AKT signaling pathways." (PMID 33718179, 2021). "In sum, our findings for the first time demonstrate that circ-LRIG3 is a tumor-promoting circRNA in HCC, it promotes hepatocarcinogenesis and metastasis through acting as a protein binding partner." (PMID 33222697, 2020). "Mice bearing tumors of circ-LRIG3-overexpressing cells had larger tumor volume and weight than mice bearing tumors of control cells." (PMID 33222697, 2020). "LRIG1 and LRIG3 show mostly tumor‐suppressive function, whereas LRIG2 frequently seems to act as an oncoprotein." (PMID 31580518, 2019). "We used immunohistochemistry to investigate LRIG1, LRIG2, and LRIG3 expression in tumour samples from a consecutive cohort of 70 PVC patients." (PMID 28841699, 2017). "The role of LRIG3 in relation to HPV neoplasms is little known." (PMID 39319059, 2024). "We first detected the protein expression level of LRIG3 in GBM tumor cells and TAMs." (PMID 36639372, 2023). "Another study showed that LRIG3 could stabilize the ErbB receptor and function as a tumor promoter in HEK293T cell line." (PMID 31245283, 2019). "In this study, we found that GBM tumor cells released LRIG3 to a soluble form through the regulation of ADAM17 and attenuate the tilt towards an M2-dominant TAM population, thus remodelling the tumor microenvironment and suppressing tumor growth." (PMID 36639372, 2023).
tumor (continued). "Clinically, HCC patients with high circ-LRIG3 expression had larger tumor size, more vascular invasion, higher edmondson’s grade and later TNM stage than patients with low circ-LRIG3 expression." (PMID 33222697, 2020). "Whereas tumor‐suppressive functions of LRIG1 and LRIG3 have been reported in malignant glioma, LRIG2 seems to act more as an oncoprotein." (PMID 31580518, 2019). "There are a further eight tumor-suppressor genes (DLEU2, CDKN2C, SPRY4, UBE2QL1, LIN9, TFPI2, LRIG3, DUSP1) and six genes serve as both oncogenes and tumor-suppressor genes (FOXO1, CAV1, KLF6, CDK6, PLK1, CTGF)." (PMID 30563222, 2018). "The leucine-rich repeats and immunoglobuline-like domains (LRIG)-1 protein functions as a tumour suppressor, but less is known about the functions of LRIG2 and LRIG3." (PMID 28841699, 2017). "The LRIG1 is a negative regulator of growth factor signaling functioning as a tumor suppressor in mice models whereas the function of LRIG2 and LRIG3 are less well defined." (PMID 25653716, 2015). "LRIG3 seems to have functions similar to LRIG1, showing a more tumor-suppressive potential." (PMID 41201961, 2025). "Molecular mechanistic investigation demonstrated that both LRIG3 and sLRIG3 inhibit the growth and invasion capabilities of GL15, U87, and PriGBM cells and tumor xenografts in nude mice through regulating the MET/phosphatidylinositol 3-kinase/Akt signaling pathway." (PMID 31245283, 2019). "A majority of the 70 tumours showed LRIG1 and LRIG2 expression in >50% of cells and demonstrated no or low LRIG3 expression." (PMID 28841699, 2017).
cancer (8 papers, 2016 to 2025). A tumor composed of atypical neoplastic, often pleomorphic cells that invade other tissues. "LRIG3 has previously been connected to several types of cancers, but Lrig3 knockout in mice also impaired cardiac function, HSPB7 encodes the heat shock protein B7, which is mostly expressed in cardiac and skeletal muscle and preserves contractile integrity." (PMID 33330662, 2020). "In cancer, the roles of LRIG1 and LRIG3 should be re-evaluated in light of their functions as BMP sensitizers." (PMID 33469151, 2021). "Four genes (DCC, EGFR, LRIG3, and RUNX1) mutated in GTKO-F0 pig No. 681 were previously found to be mutated in some human cancers." (PMID 40833781, 2025). "It was also shown that LRIG3 could negatively control the ERK pathway, which is known to be often upregulated in human cancer." (PMID 33802837, 2021). "Therefore, our data uncover the oncogenic effect of circ-LRIG3 in HCC, meanwhile provide new evidence for the important role of circRNA in cancer cell biology." (PMID 33222697, 2020).
LRIG3 also shares sentences with these, for which no sentence is quoted: cervical adenocarcinoma (2 papers); bladder cancer (1); brain tumors (1); cervical intraepithelial neoplasia (1); colorectal cancer (1); metabolic disease (1); neutropenia (1); non-small cell lung carcinoma (1); osteosarcoma (1); primary Sjogren’s syndrome (1); squamous cell cervical cancer (1).